USP11 (ubiquitin specific peptidase 11)
Diseases named in the same sentence as USP11 in open-access papers (continued):
Sharing a sentence is not in itself a finding about the gene and the disease.
tumor (continued). "Because of the inability of immunofluorescent double staining of USP11 and E-cadherin antibodies in tumor samples, we performed IHC analysis with antibodies against USP11 and E-cadherin for serial sections of the samples." (PMID 39270819, 2024). "We then ectopically expressed WT USP11 (Flag-USP11) and an enzymatically inactive mutant form of USP11, USP11-C318 A (Flag-USP11-C318 A), in luminal tumor cells." (PMID 39270819, 2024). "We found that, relative to control, Usp11 KD clearly reduced the expression of E-cadherin in luminal tumor cells." (PMID 39270819, 2024). "As a result, USP11 enhances tumor cell proliferation by deubiquitinating and stabilizing cytoplasmic p21." (PMID 35414784, 2022). "Of note, reintroducing p21-ΔNLS into USP11-depeleted cells reversed the tumor-inhibiting effect of USP11 depletion." (PMID 35414784, 2022). "For example, USP11 stabilizes eIF4B, which acts as a transcription factor to increase the mRNA translation of tumor proteins such as cMYC, BCL2, and BCL6, thereby promoting oncogenic translation." (PMID 35359344, 2022). "Excised xenograft tumors were measured 30 days after tumor cell implantation, the size and weight of the tumor formed by USP11-depleted MCF-7 cells were significantly decreased." (PMID 35414784, 2022). "Compared with mice inoculated with control cells, mice bearing USP11-depeleted MCF-7 cells showed decreased tumor growth throughout the experiment." (PMID 35414784, 2022). "Ubiquitin-specific protease 11 (USP11) was reported to induce tumor resistance to treatment through stabilizing downstream proteins by deubiquitination." (PMID 33758608, 2021). "At the 37‐day mark after inoculation, the volume and weight of the tumour formed by USP11‐depleted SK‐Mel‐28 cells significantly decreased." (PMID 33369124, 2021). "Compared with mice bearing control‐shRNA‐transfected cells, mice implanted USP11‐shRNA–cells indicated reduced tumour growth throughout the experiment." (PMID 33369124, 2021). "In this study, we confirmed that EGFR‐vIII epigenetically silenced ubiquitin‐specific protease 11 (USP11) in vitro and in vivo, which mediated tumour suppression though blocking cell cycle progression." (PMID 31993801, 2020). "We assume FK228‐induced G1/S transition arrest had an anti‐tumour effect in GBM though epigenetic remodelling to upregulate USP11 expression." (PMID 31993801, 2020). "In vivo mouse allograft generation with these transformed cells confirmed the critical tumor-suppressive function of USP11." (PMID 30733438, 2019). "IHC analysis of USP11 expression in 38 DLBCL as well as 20 reactive lymph nodes markedly displays >90% expression in tumor." (PMID 29483509, 2018). "Our findings suggest that USP11 functions as a tumor suppressor in the early stages of skin carcinogenesis associated with UV exposure." (PMID 29228550, 2017). "While all of the tumor cells at both diagnosis and relapse shared the two SNVs in CREBBP and RGS11, five additional mutations in NRF1, MARCKS, USP11, ELK1, and MYC were detected at diagnosis." (PMID 26527318, 2016). "To further investigate this, we examined whether USP11 affects EGFR expression in vivo using xenograft tumor models." (PMID 41419456, 2025). "To explore this, we used mitoxantrone as a USP11 inhibitor in a 3D tumor spheroid formation assay." (PMID 41419456, 2025). "USP11 also plays a tumor-promoting role in several cancer types." (PMID 41052634, 2025). "Furthermore, USP11 deficiency suppressed tumor spheroid formation in response to EGF, HKLM (a TLR2 agonist), and LPS (a TLR4 agonist), whereas USP11 overexpression amplified these effects." (PMID 41419456, 2025).
tumor (continued). "The function of USP11 in controlling tumor development and progression is very puzzling." (PMID 39270819, 2024). "We knocked down (KD) Usp11 in luminal tumor cells using lentiviruses." (PMID 39270819, 2024). "Despite Nrf2/ARE pathway and USP11 appeared to be critical roles in tumor, it remained unclear whether USP11 contributed to the regulation of Nrf2 in CRC." (PMID 39617751, 2024). "Previous studies have suggested that USP11 functions as a tumor suppressor and oncogenic protein." (PMID 35414784, 2022). "It has been reported that USP11 functions as a tumor suppressor and an oncogenic protein." (PMID 35414784, 2022). "USP11 is a member of the largest subfamily of cysteine protease DUBs, involving in the regulation of cell cycle, DNA repair, regulating signaling pathways, tumor development, and other important biological behaviors." (PMID 35359344, 2022). "USP11 and Ki67 levels in tumor tissues were detected via immunohistochemistry." (PMID 33685455, 2021). "However, IGF stimulation triggers AKT phosphorylation in USP11-depleted cells, resulting in tumor progression, which suggests a critical role of USP11 in the IGF-induced signaling network." (PMID 33946990, 2021). "Another DUB inhibitor, mitoxantrone, is FDA-approved to inhibit USP11 and has advanced to phase I/II clinical trials to target diseases, such as relapsed acute myeloid leukemia, neoplasms, advanced recurrent or metastatic breast cancer, multiple sclerosis, and neuromyelitis optica." (PMID 33158118, 2020). "FK228 could enhance anti‐tumour activity by upregulating expression of the tumour suppressor USP11 in GBM cells." (PMID 31993801, 2020). "FK228 could enhance anti‐tumour activity against GBM by upregulating the expression of the tumour suppressor USP11." (PMID 31993801, 2020). "Given the tumor-suppressive roles of PTEN3,32, we speculated that the loss of Usp11 might promote a variety of tumorigenic processes." (PMID 30733438, 2019). "Additionally, pre-cancerous AK in human skin and UVB-irradiated non-tumor mouse skin showed a decrease in USP11 protein levels in the epidermis as compared with normal skin." (PMID 29228550, 2017). "In addition, ROS levels and mitochondrial apoptosis-related protein expression in subcutaneous tumor tissue samples from nude mice with USP11 knockdown were significantly increased, while the expression of antioxidant molecular proteins was significantly decreased." (PMID 39617751, 2024). "Thus, USP11 exhibits two seemingly contradictory effects on tumor development." (PMID 35414784, 2022). "Furthermore, we discovered that PTEN-induced FOXO activation promotes USP11 transcription, which in turn stabilizes PTEN, suggesting that PTEN autoregulates itself through a PI3K-FOXO-USP11 feedforward loop to create a PTEN ‘integrated circuit’ that induces tumor suppression." (PMID 36385557, 2022). "Next, we tested whether USP11 functions as a tumor suppressor through PTEN regulation." (PMID 30733438, 2019). "RNA-seq analysis of tumor and matched normal tissues from 35 CRC patients identified USP11 as significantly overexpressed in tumor samples." (PMID 41419456, 2025). "Qiao’s team showed that Ubiquitin specific peptidase 11 (USP11) bound to E2F1 and promoted its stability by deubiquitination, and E2F1/USP11 formed a feedback loop to impede HCC tumor growth by inhibiting autophagy via activating ERK/mTOR pathway." (PMID 40221814, 2025).
tumor (continued). "The marked reduction in tumor spheroid size observed following mitoxantrone treatment in both EGFR- and TLR-stimulated conditions strongly suggests that USP11 is a promising therapeutic target for EGFR- or TLR-driven CRC." (PMID 41419456, 2025). "Among these, USP11—a deubiquitinating enzyme structurally and sequentially similar to USP4 and USP15—was notably overexpressed in the tumor tissues of 25 CRC patients, compared to USP4 and USP15." (PMID 41419456, 2025). "The knockdown of USP11 in both in vitro cell lines and in vivo mouse models leads to reduced POMC expression and ACTH levels, confirming its functional role in tumor behavior." (PMID 40364036, 2025). "We demonstrated that USP11 overexpression promotes HIF‐1α stabilization and enhances glycolysis through PDK1 and LDHA‐related pathways, eventually leading to tumour cell proliferation and metastasis." (PMID 38229475, 2024). "USP11 controls its stability by promoting deubiquitination of a residual protein (VGLL, a tumor suppressor) and exerts its tumor suppressor effect through the VGLL4/YAP-TEAD regulatory ring." (PMID 39185411, 2024). "Collectively, these data demonstrate that USP11 down‐regulation sensitizes human HCC cells to apoptosis and suppresses tumour growth by regulating KLF4 stability." (PMID 34114341, 2021). "Ubiquitin-specific protease 11 (USP11) deubiquitinated and stabilized VGLL4 proteins, and the inactivation of USP11 was suggested to be involved in the destabilization of VGLL4 in tumor cells." (PMID 32793503, 2020). "MRI analysis revealed the presence of larger tumor masses in the prostates of 20-week-old TRAMP;Usp11-/Y mice than in age-matched TRAMP;Usp11+/Y cohorts." (PMID 30733438, 2019). "Together, these data strongly suggest that USP11 promotes DLBCL proliferation, in part by enhancing protein translation of eIF4B-dependent oncogenes and diminishing tumor-suppressor gene expression." (PMID 29483509, 2018). "Our findings indicate that USP11 plays an important role in maintaining NER capacity, and suggest that USP11 acts as a tumor suppressor via its role in DNA repair." (PMID 29228550, 2017). "In seven cases (UCHL1, USP9X, USP11, USP10, USP22, COPS5 and COPS6), dysregulation was observed in more than one tumor type." (PMID 21283576, 2011). "The impact of USP11 on EGFR signaling was validated using USP11-KO cells, which demonstrated reduced EGFR stability and in vivo tumorigenic effect, and diminished responses to EGF stimulation in migration, proliferation, and 3D tumor spheroid assays." (PMID 41419456, 2025). "Tumor formation was significantly increased in NSG mice engrafted with Ctrl cells, whereas it was substantially reduced in mice engrafted with USP11-KO HCT-15 cells (Ctrl HCT-15 vs. USP11-KO HCT-15)." (PMID 41419456, 2025). "Moreover, USP11 inhibition by mitoxantrone significantly impaired EGFR- and TLR-driven tumor growth, highlighting USP11 as a potential therapeutic target." (PMID 41419456, 2025). "We found that USP11 was readily detected in E-cadherin-positive tumor cells but hardly detectable or weakly expressed in E-cadherin-negative tumor cells." (PMID 39270819, 2024). "Furthermore, USP11 suppresses IGF-I- or EGF-induced activation of the PI3K/AKT pathway by deubiquitination and stabilization of the tumor suppressor PTEN." (PMID 33946990, 2021). "USP11 deubiquitinates and stabilizes the vestigial-like family member 4 (VGLL4) protein, which directly competes with YAP by forming a complex with the TEA domain proteins (TEADs), thereby acting as a tumor suppressor." (PMID 33158118, 2020).
tumor (continued). "Conversely, knocking down USP11 enhanced the cell growth, invasion, and energy metabolism of PC3 PTENWT cells but not PC3 PTEN-/- cells, suggesting that USP11 exerts a PTEN-dependent tumor-suppressive function." (PMID 30733438, 2019). "Furthermore, multiple tumor nodules metastasized to lymph nodes in TRAMP;Usp11-/Y mice (~80% incidence), which was seen at a far lower incidence (< 20%) in TRAMP;Usp11+/Y mice." (PMID 30733438, 2019). "Here, we showed that USP11 involved in lnc-DILC-mediated stabilization of PTEN, suggesting that USP11 may act as a tumor suppressor in ccRCC." (PMID 31592114, 2019). "Given that USP11 appears to play a functional role in EGFR- or TLR-driven CRC progression, we investigated whether USP11 could be a viable therapeutic target for inhibiting EGFR- or TLR-driven CRC tumor growth." (PMID 41419456, 2025). "Our results demonstrate that, through its deubiquitinating activity, USP11 enhances the stability of EGFR and TRAF6, crucial mediators in these pathways, ultimately promoting CRC tumorigenesis, cell migration, proliferation, colony formation, and 3D tumor spheroid formation." (PMID 41419456, 2025). "Notably, immunohistochemical (IHC) staining with anti-EGFR antibodies revealed a significant reduction in EGFR expression in tumor tissues from NSG mice engrafted with USP11-KO HCT-15 cells compared to those with control HCT-15 cells (USP11-KO HCT-15 vs. Ctrl HCT-15)." (PMID 41419456, 2025). "We observed that the loss or depletion of Usp11 eliminated E-cadherin expression in MECs and tumor cells, and overexpression of WT USP11, not a deubiquitinase-inactive mutant form of USP11, promoted the expression of E-cadherin protein in tumor cells in vitro and in vivo." (PMID 39270819, 2024). "Collectively, our data showed that USP11 has a NONO‐dependent tumour‐promoting function." (PMID 33369124, 2021). "Nevertheless, restoring NONO expression reversed the tumour‐suppressing effect of USP11 shRNAs." (PMID 33369124, 2021). "We found that USP11 levels were high (score 2 or 3) in all sham-irradiated skin tissue (9/9), in ∼45% of the chronic UV-irradiated non-tumor tissue (4/9), and in none of the chronic UV-irradiated tumor tissue (0/9)." (PMID 29228550, 2017). "Analysis via Western blot verified that the effects of USP11 knockdown and reintroducing NONO expression were retained in these tumours." (PMID 33369124, 2021).
adenocarcinoma (2 papers, 2019 to 2023). A common cancer characterized by the presence of malignant glandular cells. "In transgenic adenocarcinoma of the mouse prostate (TRAMP) mice, the advancement of malignancy is induced following the knockout of USP11." (PMID 38139829, 2023).
infection (2 papers, 2021 to 2022). The state of being infected such as from the introduction of a foreign agent such as serum, vaccine, antigenic substance or organism. "USP11 was highly expressed in the rats that developed ICH-like symptoms but reduced after infection with lentivirus expressing sh-USP11." (PMID 34141823, 2021).
neurological disease (2 papers, 2021 to 2025). "This evidence suggests a potential connection between USP11 and neurological disease, but our understanding of the relationship between USP11 and HD is limited." (PMID 39780069, 2025).
neurodegenerative disease (1 paper, 2021). A disorder of the central nervous system characterized by gradual and progressive loss of neural tissue and neurologic function. "Taken together, our data suggested that USP11 impinges on the autophagy pathway at multiple sites and that inhibiting USP11 alleviates symptoms of proteotoxicity, which is a major hallmark of neurodegenerative diseases." (PMID 34600886, 2021).
retinal disorder (1 paper, 2019). Any disease or disorder of the retina. "Ubiquitin-specific protease 11 (USP11, also known as UHX1) was originally identified as one of the X-linked retinal disorder genes at Xp11.2321, although it is worth noting that a common deletion within the USP11 interval had been observed earlier in ovarian cancer." (PMID 30733438, 2019).
USP11 also shares sentences with these, for which no sentence is quoted: actinic keratosis (2 papers); injury (2); triple-negative breast carcinoma (2); acute kidney injury (1); acute myeloid leukemia (1); bladder cancer (1); bladder urothelial carcinoma (1); blood tumors (1); breast invasive carcinoma (1); colon adenocarcinoma (1); colorectal tumors (1); dementia (1); hemorrhage (1); Hepatic steatosis (1); idiopathic pulmonary fibrosis (1); interstitial lung disease (1); lentivirus infection (1); prostate (1); prostate adenocarcinoma (1); pulmonary arterial hypertension (1); schizophrenia (1); serous ovarian carcinoma (1).